PAGE1 (PAGE family member 1)
Synonyms: PAGE-1; GAGE-9; GAGEB1; CT16.3; AL5
Tractability: PROTAC: ubiquitination databases record sites on it.
Gene: Protein-coding gene on chromosome X (49,687,447 to 49,695,984, reverse strand). Ensembl gene ENSG00000068985.
Subcellular location (Human Protein Atlas): Nucleoli fibrillar center; Mitochondria; Nucleoplasm
Gene Ontology:
Molecular function: protein binding
Homologues: Orthologues: chimpanzee PAGE1 (98% identical), macaque PAGE1 (84% identical). Paralogues in human: GAGE10 (47% identical), GAGE1 (43% identical), GAGE13 (43% identical), GAGE12J (42% identical), GAGE2A (42% identical), GAGE12C (42% identical), GAGE12D (42% identical), GAGE12E (42% identical), GAGE12F (42% identical), GAGE12G (42% identical), GAGE12H (41% identical), GAGE2E (39% identical), and 10 more.
Diseases named in the same sentence as PAGE1 in open-access papers:
PAGE1 is named in the same sentence as 11 diseases in open-access papers, as found by Europe PMC text mining. Sharing a sentence is not in itself a finding about the gene and the disease. The quoted sentences say what the papers report.
melanoma (2 papers, 2017 to 2023). A malignant, usually aggressive tumor composed of atypical, neoplastic melanocytes. "Some genes seem to show a more specific profile depending on the tumor type, such as C17ORF104, only highly-abundant in the melanoma samples, FUT5 in colon, PAGE1 in ovarian tumor and CSNK1A1L in prostate." (PMID 29190970, 2017).
neuroblastoma (1 paper, 2024). Neuroblastoma (NB) is the most common solid, extracranial childhood tumor. "Studies have shown that CDK5R2 CYP26B1, DCAF8L1, PAGE1, and TRIM36 can be used to construct prognostic models or prognostic biomarker for HCC, rectal cancer, neuroblastoma, etc." (PMID 38649860, 2024).
pancreatic ductal carcinoma (1 paper, 2024). "PAGE1 in serum may be an immunosuppressive biomarker for pancreatic ductal carcinoma." (PMID 38649860, 2024).
papillary thyroid cancers (1 paper, 2019). "Interestingly, PAGE1 was previously identified as one of seven genes included in a radiation-induced gene signature that completely distinguished post-Chernobyl papillary thyroid cancers (PTC) from non-radiation induced PTC42." (PMID 31796844, 2019).
seminoma (1 paper, 2006). A radiosensitive malignant germ cell tumor found in the testis (especially undescended), and extragonadal sites (anterior mediastinum and pineal gland). "In terms of human testicular tumours, many CT antigens including MAGE, GAGE, PAGE-1, SSX2, NY-ESO-1, LAGE-1, and SCP-1 are also demonstrated to have higher frequency of expression in seminomas than in non-seminomas." (PMID 16479255, 2006).
cancer (4 papers, 2020 to 2024). A tumor composed of atypical neoplastic, often pleomorphic cells that invade other tissues. "Other cancer/testis antigens such as PAGE1 and NXF2 (cancer/testis antigen 39) were also found associated with this gene cluster." (PMID 33303959, 2020). "Most HCC tissues exhibited elevated protein levels of CDK5R2, CYP26B1, DCAF8L1, PAGE1, and TRIM36 in comparison to para-carcinoma tissues, as indicated by the results." (PMID 38649860, 2024). "Of 90 CTAs validated by RNA sequencing, eight CTAs (DPEP3, EZHIP, MAGEA4, MAGEB2, MAGEC2, PAGE1, PRAME, and TKTL1) were selected for immunohistochemical profiling in cancer tissues from 328 NSCLC patients." (PMID 37341056, 2023).
tumor (4 papers, 2017 to 2024). "This analysis identified TRIM36, CYP26B1, PAGE1, CDK5R2, and DCAF8L1 as a molecular signature associated with tumor aggressiveness." (PMID 38649860, 2024). "Furthermore, MAGEB2 can improve the stress tolerance of tumor cells by inhibiting the synthesis of stress granules; PAGE1 is also highly expressed in HCC cells and is considered as a potential biomarker and therapeutic target." (PMID 36173462, 2023). "CT47A1, PAGE1, MAGEA9, MAGEC2, and MAGEA1 were detected at protein level in tumor tissues (CT47A1 in 14%, PAGE1 in 23%, MAGEA9 in 11%, MAGEC2 in 59% and MAGEA1 in 34% of tumors)." (PMID 34065388, 2021). "Recognizing the critical role of m1A in tumor progression and prognosis, a reliable prognostic signature based on five DEGs characterizing autophagy among the m1A modification patterns (CDK5R2, CYP26B1, DCAF8L1, PAGE1, and TRIM36) was initially established." (PMID 38649860, 2024).
PAGE1 also shares sentences with these, for which no sentence is quoted: hepatocellular carcinoma (1 paper); ovarian tumor (1); rectal cancer (1); testicular tumours (1).